SERP1 (stress associated endoplasmic reticulum protein 1)
Description:
Interacts with target proteins during their translocation into the lumen of the endoplasmic reticulum. Protects unfolded target proteins against degradation during ER stress. May facilitate glycosylation of target proteins after termination of ER stress. May modulate the use of N-glycosylation sites on target proteins.
Synonyms: RAMP4; FLJ43424
Tractability: Antibody: UniProt predicts a signal peptide or a membrane-spanning region. PROTAC: ubiquitination databases record sites on it.
Gene: Protein-coding gene on chromosome 3 (150,541,998 to 150,603,228, reverse strand). Ensembl gene ENSG00000120742.
Subcellular location: Membrane; Endoplasmic reticulum membrane
Subcellular location (Human Protein Atlas): Endoplasmic reticulum
Pathways (Reactome):
Cellular responses to stimuli: XBP1(S) activates chaperone genes
Protein localization: Insertion of tail-anchored proteins into the endoplasmic reticulum membrane
Gene Ontology:
Molecular function: protein binding
Biological process: endoplasmic reticulum unfolded protein response; glycoprotein biosynthetic process; plasma membrane organization; protein modification process
Cellular component: cytoplasmic microtubule; cytosol; endoplasmic reticulum; endoplasmic reticulum membrane; membrane; ribosome
Genetic constraint (gnomAD): Loss-of-function variants: 5 observed, 7 expected, observed/expected ratio (o/e) 0.71, 90% interval 0.37 to 1.48. That is too few expected variants to judge how well the gene tolerates losing a copy. Missense variants: 44 observed, 71.33 expected, observed/expected ratio (o/e) 0.62, 90% interval 0.48 to 0.79. Synonymous variants: 33 observed, 26.68 expected, observed/expected ratio (o/e) 1.24, 90% interval 0.94 to 1.65.
Homologues: Orthologues: chimpanzee SERP1 (100% identical), dog SERP1 (100% identical), guinea pig SERP1 (100% identical), macaque SERP1 (100% identical), mouse Serp1 (100% identical), pig SERP1 (100% identical), rabbit SERP1 (100% identical), rat Serp1 (100% identical), zebrafish SERP1 (89% identical), zebrafish serp1 (88% identical), tropical clawed frog serp1 (76% identical), Drosophila melanogaster CG32276 (65% identical), and 2 more. Paralogues in human: SERP2 (89% identical).
Diseases named in the same sentence as SERP1 in open-access papers:
SERP1 is named in the same sentence as 48 diseases in open-access papers, as found by Europe PMC text mining. Sharing a sentence is not in itself a finding about the gene and the disease. The quoted sentences say what the papers report.
vasculitis (7 papers, 2014 to 2023). "In a prior work with the MHV68 mouse herpesviral infections, lung hemorrhage as well as vasculitis were improved with Serp-1 treatments." (PMID 37759793, 2023). "Serpins have been examined in preclinical models of severe viral infections with coagulopathy, one notable example being the use of Serp-1 treatment in the severe vasculitis/lung hemorrhage model in IFNγR−/− mouse models." (PMID 33869309, 2021). "Serp-1 has proven efficacy in models of herpes virus-induced arterial inflammation (vasculitis) and lung hemorrhage and has also proved safe in a clinical trial in patients with unstable coronary syndromes and stent implant." (PMID 33665212, 2021). "In prior work the Myxomavirus-derived anti-inflammatory serpin, Serp-1, improved survival, reducing vasculitis and pulmonary hemorrhage in MHV-68-infected IFNγR−/− mice with significantly increased IL-10." (PMID 30249047, 2018). "In a recent study in a mouse model of IVS using a lethal Mouse Herpesvirus 68 (MHV68) infection-induced vasculitis, Serp-1 markedly reduced arterial and systemic inflammation and improved survival." (PMID 25658487, 2015). "Serp‐1 is effective in multiple animal models of inflammatory lung disease and vasculitis." (PMID 37534622, 2023). "Given the efficacy of Serp-1 treatment in reducing vascular inflammation and in atherosclerosis, Serp-1 treatment was assessed in rat and mouse aortic and rat renal allograft transplant models for transplant rejection and transplant vasculitis." (PMID 37759793, 2023). "In the mouse aortic allograft transplant model, the role of the uPA/ uPAR complex and the mammalian PAI-1 serpin in Serp-1-mediated reductions in vasculitis were analyzed using donor-transplanted aortic segments from mouse models that were deficient in uPAR or PAI-1 knock out mice." (PMID 37759793, 2023). "Interestingly, peptides derived from Serp-1 are also therapeutically effective in the gammaherpesvirus-induced vasculitis model and protection imparted by both the full protein and the peptide derivatives are dependent on composition of the gut microbiome." (PMID 33869309, 2021). "In this prior study in MHV-68-infected IFNγR−/− mice, Serp-1 treatment reduced vasculitis, inflammation, and pulmonary consolidation and hemorrhage with associated increases in IL-10, suggesting a potential beneficial effect for IL-10 in MHV-68 infection in IFNγR−/− mice." (PMID 30249047, 2018). "Several RCL peptides derived from the Serp-1 RCL sequence have also been developed and tested in mouse models of vasculitis." (PMID 37759793, 2023). "Serp-1 modifies macrophage, and T helper (Th) responses in mouse aortic transplants and macrophage responses in MHV68-induced vasculitis." (PMID 25658487, 2015). "Serp-1 also reduces arterial inflammation and improves survival in a mouse herpes virus (MHV68) model of lethal vasculitis." (PMID 25354050, 2014).
glioblastoma (3 papers, 2015 to 2021). The most malignant astrocytic tumor (WHO grade IV). "Additionally, high SERP1 levels are associated with poor outcomes in glioblastoma patients; however, studies on the correlations of SERP1 with SKCM prognosis are still lacking." (PMID 34613934, 2021). "Overexpression of SERP1 reverses miR-124-induced cell death under hypoxia in glioblastoma." (PMID 33416075, 2021). "For example, miR-124 alleviates cell death in the process of AD by targeting BACE1, while increases cell death in glioblastoma by regulating TEAD1, MAPK14/p38α, and SERP1." (PMID 26041995, 2015).
osteosarcoma (3 papers, 2021 to 2023). A usually aggressive malignant bone-forming mesenchymal neoplasm, predominantly affecting adolescents and young adults. "For instance, a recent research uncovered that SERP1 can facilitate osteosarcoma progression through modulating circ_0085539/miR-526b-5p signalling axis." (PMID 38106991, 2023). "Hsa_circ_0085539 was connected with osteosarcoma progression by sponging miR-526b-5p and suppressing SERP1." (PMID 34860853, 2021).
pancreatic cancer (3 papers, 2013 to 2021). "As the first step to evaluate the role of uPA in the anti-tumor function of serpins, pancreatic cancer Hs766t was treated with uPA and Serp-1." (PMID 25798214, 2013). "Consistent with gross finding on tumor weights, serpin treatment decreased proliferation of pancreatic cancer cells in vivo as measured by Ki67 staining (P ≤ 0.001 for Serp-1 and NSP treatments)." (PMID 25798214, 2013). "Anti-tumor activity after Serp-1 treatment was also seen with MIA PaCa-2 pancreatic cancer cells (P ≤ 0.02)." (PMID 25798214, 2013). "Serp-1 and neuroserpin inhibited growth of the pancreatic cancer cell line Hs766t (P=0.03 and P=0.01, respectively) at 4 weeks after implantation." (PMID 25798214, 2013). "This suppression of cell counts in the pancreatic tumors suggests that Serp-1 and NSP inhibit macrophage invasion into the tumor." (PMID 25798214, 2013). "The effects of myxomaviral anti-inflammatory proteins, Serp-1, which inhibits uPA, plasmin and coagulation factor X, and M-T7 that inhibits C, CC, and CXC chemokines are implicated in the regulation of MDSCs in cancer models including pancreatic cancer." (PMID 31652904, 2019). "Treatments with Serp-1 and neuroserpin (a mammalian serpin and inhibitor of thrombolytic proteases), but not M-T7 were found to specifically reduce the in vivo proliferation and growth of pancreatic tumor xenografts." (PMID 31652904, 2019). "This study demonstrated that myxomaviral protein Serp-1 inhibits growth of two different pancreatic cancer cell lines in NOD/SCID mice, providing a proof-of-concept that viral anti-inflammatory protein Serp-1 has the potential to be used for therapeutic application in treatment of pancreatic cancer." (PMID 25798214, 2013). "Serp-1 also inhibited growth of a second pancreatic cancer cell line MIA PaCa-2 in mice (P=0.02)." (PMID 25798214, 2013). "Serp-1 and neuroserpin both share the capacity to inhibit uPA and tPA, and thus we postulate that the antiinflammatory/anti-tumor activity of these two proteins is secondary to inhibition of the uPA/uPA receptor (uPAR) in immune cells and/or pancreatic cancer cells." (PMID 25798214, 2013). "Also, it may interact with SERP1 to affect the prognosis of pancreatic cancer." (PMID 34094926, 2021). "Our study reported here demonstrates inhibitory activity for Serp-1 and NSP on growth of pancreatic cancer cell implants in SCID mice." (PMID 25798214, 2013). "Serp-1 and NSP treatment for 14 days starting from day one, significantly reduced growth of the pancreatic cancer cell line Hs766t after transplant into NOD/SCID mice (P<0.03 and P< 0.01, respectively)." (PMID 25798214, 2013). "On immunohistochemical staining analysis, the number of positively stained macrophages in the pancreatic cancer tissue isolates was significantly decreased in NSP and Serp-1 treated mice (P<0.001), when compared to saline treated controls." (PMID 25798214, 2013). "In order to examine which inflammatory cells were potentially modified by Serp-1 treatment we examined mouse splenocytes from NOD/SCID mice with pancreatic cancer cell implants with and without Serp-1 treatments, using flow cytometry analysis." (PMID 25798214, 2013). "This is consistent with our observation that Serp-1 fails to inhibit pancreatic cancer cell proliferation in vitro, but does block cancer growth in vivo." (PMID 25798214, 2013). "A time course study further confirmed inhibition of Hs766t pancreatic cancer growth by 4-weeks with Serp-1 treatment (P< 0.02), but without significant inhibition at earlier follow-up times (P<0.02 at 4 weeks)." (PMID 25798214, 2013).
pancreatic ductal adenocarcinoma (3 papers, 2020 to 2024). An infiltrating adenocarcinoma that arises from the epithelial cells of the pancreas. "Furthermore, in pancreatic ductal adenocarcinoma, SRPRB was regulated by SERP1, a prognostic marker, acting on its development." (PMID 38440732, 2024).
Sepsis (3 papers, 2021 to 2024). Sepsis is defined as life-threatening organ dysfunction caused by a dysregulated host response to infection. "We investigated the effect of exosomal miR-1-3p and its target gene SERP1 on endothelial cells during sepsis." (PMID 33416075, 2021). "These suggest a potential therapeutic role of miR-1-3p and SERP1 in improving sepsis-induced lung injury and will be easily translated into clinical practice." (PMID 33416075, 2021). "This is the first time that the relationship between miR-1-3p and SERP1 has been elucidated and may provide potential new targets against sepsis-induced lung injury." (PMID 33416075, 2021). "Furthermore, miR-1-3p, present in plasma exosomes, is upregulated in sepsis, leading to a reduction in the expression of stress-related endoplasmic reticulum protein 1 (SERP1), thus inducing endothelial cell damage and dysfunction, and contributing to the onset of sepsis." (PMID 39104595, 2024). "MiR-1-3p and its target gene SERP1 could be intervention targets for lung injury in sepsis." (PMID 33416075, 2021). "MiR-1-3p and SERP1 may be promising therapeutic candidates for sepsis-induced lung injury." (PMID 33416075, 2021).
skin cutaneous melanoma (3 papers, 2021 to 2025). "Low SERP1 expression in patients with SKCM may be a manifestation of a relatively moderate magnitude of ER stress, thus maintaining the survival of cutaneous melanoma cells." (PMID 34613934, 2021).
Arthritis (2 papers, 2015 to 2023). Inflammation of a joint. "Rats that were administered Serp-1 at 50 μg/kg via intravenous (IV) injections had reduced clinical arthritis, with reduced joint swelling when it was given at the time of inducing the disease." (PMID 37759793, 2023). "Serp-1 has been previously extensively tested in animal models of vascular disease and arthritis with demonstrated significant prolonged reductions in plaque growth and inflammation after early short term treatment." (PMID 25658487, 2015).
breast carcinoma (2 papers, 2013 to 2018). "The reason for the lack of MDSC response in this breast cancer model is unknown but is consistent in that this lack of activity is associated with the lack of Serp-1 efficacy on this breast cancer cell isolate." (PMID 25798214, 2013). "Serp-1 may not inhibit breast cancer growth even with a significant level of uPA expression in the cancer cells themselves, if there is no associated increase in expression of uPA or uPAR in TAM or MDSC." (PMID 25798214, 2013). "Growth of the human breast cancer line MDA231 was not inhibited by Serp-1." (PMID 25798214, 2013). "In contrast, growth of the breast cancer cell line MDA231 after transplant into NOD/SCID mice was not altered by serpin treatment (P=0.76 and 0.70, respectively for NSP and Serp-1)." (PMID 25798214, 2013). "MDA231 breast cancer cell proliferation after implant into SCID mice was not reduced by serpin treatment (P=0.31 and 0.08, NSP and Serp-1 respectively)." (PMID 25798214, 2013). "However, in NOD/SCID mice transplanted with breast cancer MDA231 cells, the MDSC population was neither increased after tumor growth nor reduced by Serp-1 treatment." (PMID 25798214, 2013).
coronary disease (2 papers, 2014 to 2015). "Serp-1 also reduced markers of myocardial injury in a Phase IIa clinical trial for unstable coronary disease." (PMID 25658487, 2015). "In addition, Serp-1 demonstrated safety and efficacy in patients with unstable coronary disease and stent implant, reducing markers of myocardial damage." (PMID 25354050, 2014).
endometritis (2 papers, 2024 to 2025). An acute or chronic, usually bacterial infectious process affecting the endometrium. "TLR4, IL-8, IL-17, NFKB, SLCA11A1, NCF4, Keap1, HMOX1, OXSR1, ST1P1, and SERP1 were manifestly expressed at much higher levels in the buffaloes with endometritis." (PMID 39195794, 2024). "The buffaloes with endometritis had considerably higher expression levels of TLR4, IL-8, IL-17, NFKB, SLCA11A1, NCF4, Keap1, HMOX1, OXSR1, ST1P1, and SERP1." (PMID 39195794, 2024). "Our findings showed that the buffaloes with endometritis had significantly higher TLR4, IL-8, IL-17, NFKB, SLCA11A1, NCF4, Keap1, HMOX1, OXSR1, ST1P1, and SERP1 expression levels." (PMID 39195794, 2024). "The following genes were assessed for their expression levels using real-time PCR in both the normal and endometritis-affected buffaloes: immune (TLR4, IL-8, IL-17, NFKB, SLCA11A1, and NCF4) and antioxidant (SOD, CAT, NDUFS6, Nrf2, Keap1, PRDX2, HMOX1, OXSR1, ST1P1, and SERP1)." (PMID 39195794, 2024).
melanoma (2 papers, 2018 to 2021). A malignant, usually aggressive tumor composed of atypical, neoplastic melanocytes. "Low SERP1 expression correlated with several clinical variables, such as T stage, pathologic stage, Breslow depth, Melanoma ulceration, and radiation therapy." (PMID 34613934, 2021). "Given that multiple targeted immune checkpoint blockade therapies, especially PD-1 and CTLA4, have shown significant efficacy in melanoma treatment, SERP1 expression levels in SKCM patients may also influence the efficacy of immunotherapy." (PMID 34613934, 2021). "SERP1 expression level significantly related to the T stage (p = 0.037), Pathologic stage (p = 0.009), Radiation therapy (p = 0.013), Breslow depth (p < 0.001) and Melanoma ulceration (p = 0.043)." (PMID 34613934, 2021). "We also observed significant associations between low SERP1 expression and OS with several patient and clinical parameters including race, age, TNM stage, pathologic stage, absence of radiation therapy, tumor tissue site, melanoma ulceration, and Melanoma Clark Level." (PMID 34613934, 2021).
myxoma (2 papers, 2008 to 2018). A benign soft tissue neoplasm characterized by the presence of spindle and stellate cells, lobulated growth pattern, and myxoid stroma formation. "The secreted myxoma viral serpin, Serp-1 exerts profound anti-inflammatory activity in a wide range of animal models." (PMID 18949070, 2008).
Pulmonary hemorrhage (2 papers, 2018 to 2021). Pulmonary hemorrhage is a bleeding within the lungs. "Meanwhile, Serp-1 reduces the downstream protease cascade by modulating the coagulation and fibrinolysis process, thereby preventing further destruction of lung tissue structure and pulmonary hemorrhage." (PMID 33665212, 2021).
unstable angina (2 papers, 2020 to 2022). "Of central interest to the translational potential of virus-derived immune-modulating biologics, Serp-1 was examined in patients with unstable coronary syndromes, unstable angina and small heart attacks with coronary stent implant, in the first human clinical trial of a viral protein." (PMID 32244484, 2020). "In this trial, Serp-1 was administered immediately after coronary stent implant in patients with unstable coronary syndromes, unstable angina, and non-ST elevation myocardial infarctions, where acute chronic plaque inflammation is seen." (PMID 35625891, 2022).
Allergy (1 paper, 2021). An allergy is an immune response or reaction to substances that are usually not harmful. "Pathways related to intracellular signalling pathway, stress response, VEGF and MTOR related, the latter showed in the last years to be related with allergy; and oxidative phosphorylation are up-regulated, like FOXP1, SERPIN family, SOD2, caspase family, PGF, CYB5B, SERP1 and SLC25A4." (PMID 34784380, 2021).
aneurysm (1 paper, 2023). Bulging or ballooning in an area of an artery secondary to arterial wall weakening. "The MyxV Serp-1 gene sequence has been mutated in prior work wherein Serp-1 anti-inflammatory activity was either lost or led to excess inflammation with aneurysm development." (PMID 37759793, 2023).
arteritis (1 paper, 2015). An inflammatory process affecting an artery. "Here we examine Serp-1 treatment of human temporal artery (TA) biopsies from patients with suspected TA GCA arteritis after implant (TAI) into the aorta of immunodeficient SCID (severe combined immunodeficiency) mice." (PMID 25658487, 2015).
breast tumor (1 paper, 2025). "Then, in contrast to normal breast tissue, breast tumor tissue had considerably lower MAOB expression levels and higher levels of CYCS, XBP1, HSPA4, APEX1, and SERP1." (PMID 41367017, 2025).
Duchenne muscular dystrophy (1 paper, 2022). Duchenne muscular dystrophy (DMD) is a neuromuscular disease characterized by rapidly progressive muscle weakness and wasting due to degeneration of skeletal, smooth and cardiac muscle. "In this initial study, we examined whether pegylated Serp-1 (PEGSerp-1) treatment would ameliorate chronic inflammation in a mouse model for Duchenne muscular dystrophy." (PMID 35625891, 2022).
Impaired glucose tolerance (1 paper, 2019). An abnormal resistance to glucose, i.e., a reduction in the ability to maintain glucose levels in the blood stream within normal limits following oral or intravenous administration of glucose. "The genetic ablation of SERP1 showed that the SERP1−/− mice had growth retardation, increased mortality, impaired glucose tolerance, and ER stress." (PMID 31461934, 2019).
Large vessel vasculitis (1 paper, 2019). A type of vasculitis (inflammation of blood vessel walls) affecting large arteries such as the aorta and branches of the aorta. "In other work, we have demonstrated that treatment with Serp-1, a member of the serpin superfamily of proteins, as well as peptides derived from the Serp-1 reactive center loop (RCL), reduce severity and prolong survival in a lethal, herpesvirus-induced model of large vessel vasculitis." (PMID 31160886, 2019).